CES1 (carboxylesterase 1)
Description:
Involved in the detoxification of xenobiotics and in the activation of ester and amide prodrugs. Hydrolyzes aromatic and aliphatic esters, but has no catalytic activity toward amides or a fatty acyl-CoA ester. Hydrolyzes the methyl ester group of cocaine to form benzoylecgonine. Catalyzes the transesterification of cocaine to form cocaethylene. Displays fatty acid ethyl ester synthase activity, catalyzing the ethyl esterification of oleic acid to ethyloleate. Converts monoacylglycerides to free fatty acids and glycerol. Hydrolyzes of 2-arachidonoylglycerol and prostaglandins. Hydrolyzes cellular cholesteryl esters to free cholesterols and promotes reverse cholesterol transport (RCT) by facilitating both the initial and final steps in the process. First of all, allows free cholesterol efflux from macrophages to extracellular cholesterol acceptors and secondly, releases free cholesterol from lipoprotein-delivered cholesteryl esters in the liver for bile acid synthesis or direct secretion into the bile.
Synonyms: ACAT; CE-1; hCE-1; CEH; REH; TGH; CES2; SES1; HMSE; HMSE1; CES1A1; CES1A2; PCE-1
Tractability: Small molecule: a structure with a bound ligand is known; a high-quality ligand is known; it has a high-quality binding pocket; it belongs to a druggable protein family. Antibody: UniProt predicts a signal peptide or a membrane-spanning region. PROTAC: ubiquitination databases record sites on it; its protein half-life has been measured; a small molecule that binds it is known.
Target class: Enzyme; Hydrolase
Safety:
Unwanted effects reported when the protein is acted on. In parentheses: how it was acted on, where the effect was seen, and who reports it.
adjusted trough concentrations of dabigatran (source: ClinPGx)
bleeding (source: ClinPGx)
overall capecitabine-related toxicity (source: ClinPGx)
overall early-onset capecitabine-related toxicity (source: ClinPGx)
Gene: Protein-coding gene on chromosome 16 (55,802,845 to 55,833,337, reverse strand). Ensembl gene ENSG00000198848.
Subcellular location: Endoplasmic reticulum lumen; Cytoplasm; Lipid droplet
Subcellular location (Human Protein Atlas): Endoplasmic reticulum
Pathways (Reactome):
Drug ADME: Aspirin ADME
Metabolism: Phase I - Functionalization of compounds
Metabolism of proteins: Metabolism of Angiotensinogen to Angiotensins
Muscle contraction: Physiological factors
Gene Ontology:
Molecular function: carboxylesterase activity; methylumbelliferyl-acetate deacetylase activity; sterol ester esterase activity; retinyl-palmitate esterase activity
Biological process: cellular response to cholesterol; cellular response to low-density lipoprotein particle stimulus; cholesterol biosynthetic process; cholesterol homeostasis; cholesterol metabolic process; epithelial cell differentiation; medium-chain fatty acid metabolic process; negative regulation of cholesterol storage; positive regulation of cholesterol efflux; positive regulation of cholesterol metabolic process; regulation of bile acid biosynthetic process; regulation of bile acid secretion; reverse cholesterol transport; cholesterol ester hydrolysis involved in cholesterol transport; response to toxic substance; short-chain fatty acid catabolic process; retinol metabolic process
Cellular component: cytoplasm; endoplasmic reticulum; endoplasmic reticulum lumen; lipid droplet; cytosol
Genetic constraint (gnomAD): Loss-of-function variants: 50 observed, 49.77 expected, observed/expected ratio (o/e) 1, 90% interval 0.8 to 1.27. The upper end of that interval is the gene's LOEUF score, 1.27, which puts it in group 5 of 6, group 1 being the genes least tolerant of losing a copy. Missense variants: 534 observed, 492.54 expected, observed/expected ratio (o/e) 1.08, 90% interval 1.01 to 1.16. Synonymous variants: 202 observed, 186.13 expected, observed/expected ratio (o/e) 1.09, 90% interval 0.97 to 1.22.
Homologues: Orthologues: macaque CES1 (93% identical), chimpanzee CES1 (84% identical), mouse Ces1d (78% identical), rat Ces1e (77% identical), rat Ces1dl1 (77% identical), mouse Ces1g (74% identical), guinea pig Ces1d (72% identical), pig CES1 (71% identical), mouse Ces1h (71% identical), rat Ces1f (68% identical), mouse Ces1b (66% identical), mouse Ces1c (65% identical), and 54 more. Paralogues in human: CES2 (46% identical), CES4A (43% identical), CES3 (43% identical), CES5A (42% identical), NLGN3 (35% identical), NLGN2 (34% identical), NLGN4X (34% identical), NLGN4Y (34% identical), NLGN1 (33% identical), CEL (32% identical), ACHE (32% identical), BCHE (31% identical), and 1 more.
Diseases named in the same sentence as CES1 in open-access papers:
CES1 is named in the same sentence as 109 diseases in open-access papers, as found by Europe PMC text mining. Sharing a sentence is not in itself a finding about the gene and the disease. The quoted sentences say what the papers report.
Obesity (21 papers, 2009 to 2026). Accumulation of substantial excess body fat. "These unadjusted associations identified species that have been associated with insulin resistance and obesity for the protein (eg, CES1, INHBC, RTN4R), metabolite (α-aminoadipate, butyryl carnitine, tyrosine), and lipid (TG and DG species) assays." (PMID 39657693, 2025). "Previous reports have highlighted the key role of CES1 in liver lipid metabolism and associated its alterations with obesity, hepatic steatosis, hyperlipidemia, and an increased risk of cardiovascular disease." (PMID 38034016, 2023). "It has been reported that CES1 mRNA abundance was positively correlated with clinical parameters of adiposity, which also suggests a role of CES1 in the development of obesity-associated phenotypes." (PMID 28677105, 2018). "The aim of this study was to examine CES1 expression in human adipose tissue in relation to obesity, weight loss, adipocyte size, adipose tissue location, and lipolysis." (PMID 19332024, 2009). "Taken together, our data show that increased CES1 expression is associated with obesity and markers of metabolic dysfunction indicating that CES1 plays a role in human metabolism, however, the mechanisms are unclear." (PMID 19332024, 2009). "Taken together, our results indicate that adipose tissue expression of CES1 is tightly linked to obesity, amount of body fat, and adipocyte fat content." (PMID 19332024, 2009). "CES1 also participated in obesity-induced hepatic steatosis, inactivation, and CES1 deficiency in obesity animal models induced by high-fat diet could improve the development of liver steatosis and steatohepatitis." (PMID 39227971, 2024). "In this study, we first presented a higher serum level of CES1 in both the MASLD and MetS groups of children with obesity and the serum CES1 levels were significantly associated with lipid metabolic disturbance, abnormal glucose metabolism and circulating adipokines." (PMID 39227971, 2024). "Therefore, our findings were indirectly supported by several studies that revealed a positive correlation between CES1 expression and the risk of obesity and MetS, which share common metabolic parameters with NAFLD." (PMID 34234263, 2021). "Ces1/Es-x might represent an attractive pharmacological target for the treatment of lipid abnormalities associated with obesity, insulin resistance and fatty liver disease." (PMID 23145182, 2012). "In previous studies, the expression of CES1 has been found to be higher in large compared to small adipocytes from the same biopsy and upregulated in adipose tissue in individuals with obesity." (PMID 41077621, 2026). "Our study aimed to investigate the association between CES1 and metabolic syndrome (MetS) and metabolic dysfunction associated steatotic liver disease (MASLD) in children with obesity in China." (PMID 39227971, 2024). "The most interesting finding in this study was that serum CES1 levels were significantly associated with lipid metabolism (ALT, AST, TG, TC, LDL-C), glucose metabolism (FBI, HOMA-IR) and obesity-related secreted proteins (adiponectin, leptin, GDF15, IGF-1)." (PMID 39227971, 2024). "The deficiency of Rel-A in MEFs and human CRC cell lines leads to the alteration of lipidomic profiles via carboxylesterase 1(CES1), connecting obesity-related inflammation with lipid metabolism in aggressive forms of CRC." (PMID 39493763, 2024). "Considering the network of proteins between control and obese groups, GUSB and CES1 are slightly more expressed in individuals with obesity, while significantly higher expression of both can be observed in T2D." (PMID 38732002, 2024). "In our study, we found that serum CES1 levels were significantly higher in children with obesity diagnosed as MASLD or MetS which was consistent with previous studies." (PMID 39227971, 2024). "CES1 expression was increased during the differentiation of adipocytes and is higher in adipose tissue of patients with obesity." (PMID 39227971, 2024).
Obesity (continued). "Treatment of Ces1 inhibitors to obesity mice induced by a high fat diet and db/db mice improved multiple features of metabolic disorders, including decreased weight gain, improved lipid and glucose metabolisms and improved liver steatosis." (PMID 39227971, 2024). "Dysregulation of CES1 has been associated with the development of diseases such as diabetes, obesity, and cancer, with abnormal expression of CES1 observed in various cancers including liver, lung, colorectal, and prostate cancer." (PMID 39574476, 2024). "In summary, this study indicated that serum CES1 levels were increased in children with obesity diagnosed as MASLD and MetS." (PMID 39227971, 2024). "Given the critical role of human CES1 (hCES1) in metabolizing cholesteryl esters, inhibitors of hCES1 have the potential to treat hypertriglyceridemia, obesity, type 2 diabetes and atherosclerosis." (PMID 36615256, 2022). "Carboxylesterase 1 (CES1), a member of the serine esterase family, primarily participated in adipose tissue lipolytic activity, and is linked to obesity or weight loss." (PMID 34439958, 2021). "The major hepatic serine hydrolase activities, carboxylesterase 1 (CES1) and fatty acid synthase, were unaltered in human obesity." (PMID 28099843, 2017). "Furthermore, elevated serum CES1 levels were independently associated with higher risk of MASLD and MetS in children with obesity in China." (PMID 39227971, 2024). "All of the studies presented above illustrated that an increased level of CES1 may have harmful effect on the development of obesity-related disorders and inhibiting the activity of CES1 may improve metabolic disorders of obesity." (PMID 39227971, 2024). "Our findings suggest that pharmacological interventions leading to augmented Ces1/Es-x activity might result in the alleviation of hyperlipidemia, obesity, insulin resistance and fatty liver disease." (PMID 23145182, 2012). "Although recent advances demonstrated the relevance of carboxylesterases, mainly the CES1/Ces1 and CES2/Ces2 families, to metabolic diseases such as obesity and fatty liver disease, differences and similarities among carboxylesterases were elucidated." (PMID 37339977, 2023). "Thus, the specific restoration of liver CES2/Ces2 expression, but not CES1/Ces1, can be a potential strategy to overcome obesity and fatty liver disease." (PMID 37339977, 2023).
Hepatic steatosis (13 papers, 2012 to 2025). Steatosis is a term used to denote lipid accumulation within hepatocytes. "Taken together, hepatic CES1 has a protective role in alcohol induced hepatic steatosis and its deficiency worsens hepatic steatosis by inducing DNL and liver injury in ALD." (PMID 35864895, 2022). "Carboxylesterase1/esterase-x (Ces1/Es-x) deficient mice become obese, hyperlipidemic and develop hepatic steatosis even on standard chow diet." (PMID 23145182, 2012). "Indeed, we recently revealed that HNF4 is involved in the development of liver steatosis caused by loss of function of Ces1 in diet-induced obese mice." (PMID 36472914, 2023). "Thus, Ces1 deficiency results in hepatosteatosis, and albeit to a much lower degree, there is evidence for microvesicular hepatic steatosis in Nrf2-KO animals." (PMID 33103077, 2020). "Although CES1 has been implicated in hepatic steatosis, a recent study has shown that CES1 may have potential as a biomarker to distinguish hepatocellular carcinoma (HCC) from cirrhosis." (PMID 24743702, 2014). "Previous studies have demonstrated that carboxylesterase 1 (CES1) regulates hepatic triglyceride metabolism and protects against liver steatosis." (PMID 27075303, 2016). "On the other hand, CES1 knockout mice are characterized by a gain in weight, hepatic steatosis and hyperinsulinemia, thereby supporting a role for CES1 in the regulation of fatty acids." (PMID 24743702, 2014). "Therefore, pharmacological inactivation of human TGH (CES1) could potentially ameliorate fatty liver disease, and prevent progression from simple steatosis to NASH." (PMID 27181051, 2016). "Thus, the role of CES1 in hepatic steatosis is largely unknown." (PMID 34234263, 2021). "Expression of Ces1 was induced during 3T3-L1 adipocyte differentiation, and administration of Ces1 inhibitors to HFD fed mice or db/db mice protected from weight gain reduced plasma lipids, ameliorated liver steatosis, and improved glucose tolerance." (PMID 36978789, 2023). "An unexpected finding in this study is that liver-specific knockdown, but not global inactivation, of CES1 aggravates ethanol-induced liver steatosis." (PMID 27075303, 2016). "In this study we found that mice lacking triacylglycerol hydrolase (TGH, also known as carboxylesterase 3 or carboxylesterase 1d) are protected from high-fat diet (HFD) - induced hepatic steatosis via decreased lipogenesis, increased fatty acid oxidation and improved hepatic insulin sensitivity." (PMID 27181051, 2016).
hepatocellular carcinoma (11 papers, 2012 to 2026). A malignant tumor that arises from hepatocytes. "CES1 has also been associated with the prognosis of various cancers, i.e., prostate cancer, hepatocellular carcinoma, and colorectal cancer." (PMID 40771823, 2025). "Notably, targeting the CES1/PPARα/stearoyl-CoA desaturase 1 pathway has been reported to enhance the efficacy of cisplatin in hepatocellular carcinoma models, with coadministration reducing tumor growth in xenografted mice." (PMID 40650205, 2025). "The analysis of TCGA tumor patient data revealed that high CES1 expression was associated with poor prognosis in various types of tumors including adrenocortical carcinoma, bladder cancer, HNSCC, lung squamous cell carcinoma, and hepatocellular carcinoma." (PMID 39574476, 2024). "As in mouse cells and tissues, treatment with TBE-31 or the naturally occurring Nrf2 activator sulforaphane (SFN) upregulated the expression of CES1 in the human hepatoma cell line HepG2, which has high basal levels of CES1, in a manner resembling that of NQO1 and GCLC." (PMID 33103077, 2020). "Overexpression of Ces1/Es-x in McArdle RH-7777 (rat hepatoma) cells decreased TG accumulation and decreased VLDL secretion, suggesting that the carboxylesterase might negatively regulate TG storage." (PMID 23145182, 2012). "In hepatocellular carcinoma (HCC), suppression of CES1 leads to a significant reduction in lipid signaling molecules of PPARα/γ, with a notable downregulation of the PPARα/γ target gene SCD, which is associated with tumor metastasis, recurrence, and chemoresistance." (PMID 39472448, 2024). "Interestingly, CES1 mRNA expression exhibited a bimodal distribution in certain cancers like HNSCC, lung squamous-cell carcinoma, hepatocellular carcinoma, and thyroid cancer." (PMID 39574476, 2024). "Moreover, the normal upregulation of CES1, which activates the PPAR α-SCD signaling axis, is believed to enhance lipid metabolism and potentially contribute to cisplatin resistance in hepatocellular carcinomas." (PMID 39574476, 2024).
colorectal cancer (10 papers, 2015 to 2025). A primary or metastatic malignant neoplasm that affects the colon or rectum. "CES1 is a metabolic lipase regulated by NF-κB and is known to support fatty acid oxidation and energy balance in aggressive colorectal cancers." (PMID 40650205, 2025). "Carboxylesterase 1 (CES1) is an NF-κB-regulated lipase that links inflammation and lipid metabolism, supporting the adaptation of progressive colorectal cancer (CRC) to energy stress." (PMID 39472448, 2024). "Carboxylesterase 1 (CES1)/triacylglycerol hydrolase is upregulated in obese patients with colorectal cancer, thus guiding cancer development by reinforcing triacylglycerol degradation and FAO94." (PMID 34931768, 2021). "In particular, CES1 may represent an interesting molecular target for RA or its derivatives in the context of anticancer therapy for aggressive colorectal cancers." (PMID 40650205, 2025). "Hence, the inhibition of Ces1d/CES1 through genetic or pharmacologic means resulted in the death of colorectal cancer (CRC) cells under conditions of nutrient deprivation in laboratory settings and reduced CRC growth in animal models." (PMID 38933330, 2024). "Increased CES1 expression was also shown to be associated with reduced survival rate in overweight individuals with colorectal cancer (CRC) but not in non-overweight patients." (PMID 38933330, 2024). "In colorectal cancer (CRC), RelA upregulates carboxylesterase 1 (CES1), mobilizing free fatty acids (FFAs) from lipid droplets to fuel β-oxidation (FAO) during starvation." (PMID 40562870, 2025).